DYSF (dysferlin)
Diseases named in the same sentence as DYSF in open-access papers (continued):
Sharing a sentence is not in itself a finding about the gene and the disease.
dysferlinopathy (continued). "Those cases with two DYSF variants identified (JF198, C155, JF244, JF173, JF255) or one pathogenic DYSF variant (JF251) are the most likely to have dysferlinopathy, and continued analysis to reclassify the DYSF variants as pathogenic and/or to identify the second DYSF variant needs to be performed." (PMID 36983702, 2023). "It is known that DYSF is highly expressed in blood monocytes and we and others have previously shown that DYSF protein expression in blood is a highly effective biomarker for dysferlinopathy." (PMID 36983702, 2023). "Although the use of AAV–Nano-Dysferlin showed immunofluorescence in approximately 30% of treated fibers, there are currently insufficient data on the application of nanodysferlin for muscle tissue restoration in dysferlinopathies." (PMID 37686363, 2023). "Dysferlinopathies are characterized by varied and complicated phenotypes, which makes the confirmation of the absence of dysferlin in the muscle and the detection of DYSF mutations critical for their diagnosis." (PMID 36464789, 2023). "Collective results indicate that membrane repair does not depend upon calpain cleavage within exon 40a and that ~ 10–20% of WT dysferlin protein expression is sufficient to maintain the muscle lipidome, proteome and membrane repair capacity to crucially prevent development of dysferlinopathy." (PMID 36653852, 2023). "In aged dysferlin null mice and individuals with dysferlinopathy, lack of dysferlin alters expression of many dysferlin-associated proteins including AHNAK, Annexin A2, Calpain-3, Caveolin-3 and MG53." (PMID 36653852, 2023). "Dysferlinopathy, now classified as limb-girdle muscular dystrophy R2, is an autosomal recessive limb-girdle muscular dystrophy (LGMD) caused by pathogenic variants in the DYSF gene located on chromosome 2p13 that encodes the protein dysferlin." (PMID 35135626, 2022). "Dysferlinopathy is an autosomal recessively inherited muscular dystrophy caused by mutations in the DYSF gene, which encodes the muscle-specific protein dysferlin, and its deficiency leads to sarcolemma repair abnormalities and secondary inflammatory activation." (PMID 36362794, 2022). "When taken together with the data presented herein, human dysferlinopathies, which result in LGMD2B and MM, could be another type of MD with characteristic dyslipidemia." (PMID 34366880, 2021). "In the context of therapies, these results suggest that the dysferlin transcript containing exon 40a could be restored in patients affected with dysferlinopathies." (PMID 34888307, 2021). "Similarly, dysferlinopathies are progressive muscle disorders that include LGMD R2 and Miyoshi myopathy (MM) and are caused by mutations in the dysferlin (DYSF) gene, which disrupt muscle membrane resealing." (PMID 34502539, 2021). "Since the etiology of dysferlinopathies is genetic, a putative therapeutic solution could be found using gene therapy (providing a normal copy of dysferlin) or gene repair (CRYSPR-Cas9)." (PMID 32825681, 2020). "Given the molecular similarities of Fer1L5 with dysferlin we argue that Fer1L5 may also have a role in the dysferlin repair pathway but further study will give an insight how Fer1L5 functions as a therapeutic target for the dysferlinopathies." (PMID 33182221, 2020). "Limb-girdle muscular dystrophy type 2B (LGMDR2) and Miyoshi myopathy (MM) caused by variants in the dysferlin gene, DYSF, are the two major clinical types of dysferlinopathy, characterized by proximal muscle-weakness, difficulty in running and climbing stairs, and increased fatigue." (PMID 33250842, 2020). "In agreement with this interpretation, presynaptic dysferlin deficiency has been shown to reduce the ACh release and promote muscle changes reminiscent of LGMD2B dysferlinopathy and it has been shown that dysferlin plays a critical role in the trafficking of proteins." (PMID 32825681, 2020).
dysferlinopathy (continued). "Dysferlinopathies are caused by lack of functional dysferlin, a membrane-associated calcium-binding protein involved in membrane repair." (PMID 32224495, 2020). "Dysferlinopathies are caused by the lack of functional dysferlin, which is a key protein involved in membrane repair processes causing Myoshi myopathy or dysferlin-related limb girdle muscular dystrophy (LGMD R2)." (PMID 33255644, 2020). "Muscular dystrophies induced by mutations in DYSF gene, which encodes a protein named dysferlin, leads to the complete absence of the protein and are grouped as dysferlinopathies." (PMID 32825681, 2020). "At present it is not clear how exactly loss-of-function mutations of DYSF and a decrease of the corresponding protein expression level lead to the development of dysferlinopathies." (PMID 32106631, 2020). "Alterations in dysferlin expression, such as those occurring in dysferlinopathies, could then potentially affect actin dynamics in muscle cells." (PMID 31861684, 2019). "Noteworthy, the poor G-actin incorporation in dysferlinopathy myoblasts was restored by expression of both N- and C-terminal regions of dysferlin; however, the contribution of these dysferlin regions to annexin A2 distribution remains unclear." (PMID 31861684, 2019). "The dysferlinopathies represent a heterogeneous group of late-onset muscle disease, including limb girdle muscular dystrophy type 2B (LGMD2B), which are caused by mutations in the dysferlin gene." (PMID 31160583, 2019). "Dysferlinopathies are a group of autosomal recessive muscular dystrophies caused by mutations in the dysferlin gene, DYSF, and is typified by markedly reduced or absent dysferlin protein on immunohistochemical staining in muscle." (PMID 29879922, 2018). "The absence of dysferlin causes dysferlinopathy, while defects in α-, β-, γ-, or δ-sarcoglycan (SG) genes cause LGMD2D, LGMD2E, LGMD2C, and LGMD2F, respectively." (PMID 28219397, 2017). "The typical diagnostic procedure for dysferlinopathy diagnosis has been to identify absent or reduced dysferlin protein levels and then sequence the dysferlin gene." (PMID 27602406, 2016). "Mutations in the dysferlin gene (DYSF) cause myopathies including Miyoshi myopathy (MM), limb girdle muscular dystrophy type 2B (LGMD2B), and distal anterior compartment myopathy, which are collectively called the dysferlinopathies." (PMID 26579332, 2015). "Here, we demonstrate that normal fibroblasts express the dysferlin protein, whereas those from a dysferlinopathy patient and SJL/6J mice show decreased dysferlin protein levels as well as insufficient membrane repair, similar to that observed in dysferlin-deficient myotubes." (PMID 26579332, 2015). "On the other hand, the absence of T and B lymphocytes in dysferlin deficient mice (animal model of dysferlinopathy) was shown to improve the skeletal muscle regeneration." (PMID 26613733, 2015). "Similarly to dysferlinopathies, dysferlin is prominently reduced in the muscle fibre sarcolemma in sIBM muscle biopsies." (PMID 24948216, 2014). "The contribution of X-ROS to the enhanced sensitivity to mechanical stress experienced by dysferlin-null muscle could further contribute to the muscle degeneration and myopathy that occur in dysferlinopathies." (PMID 24639655, 2014). "Mutations in the dysferlin gene cause allelic autosomal recessive disorders including limb girdle muscular dystrophy type 2B (LGMD2B), Miyoshi myopathy and distal anterior compartment myopathy, collectively known as the dysferlinopathies." (PMID 22720081, 2012). "In conclusion, we have shown that AAV5.dysferlin delivery is a very promising therapeutic approach that could restore functional deficits in dysferlinopathy patients." (PMID 22720081, 2012). "The findings from this latter study suggested that studying the expression of dysferlin protein in these more accessible cells could be a reliable method to diagnose dysferlinopathies and a valid alternative to muscle biopsy." (PMID 22194990, 2011).
dysferlinopathy (continued). "Understanding the dimeric nature of dysferlin is an essential step in revealing the mechanisms of dysferlin-mediated membrane repair and developing therapeutic drugs that could be useful in the treatment of dysferlinopathies." (PMID 22110769, 2011). "Indeed, when the clinical suspicion of dysferlinopathy is high, dysferlin in PBM can be studied even before the muscle biopsy is taken." (PMID 22194990, 2011). "Meanwhile, the DYSF variant was not considered to be an explanation for this patient’s disease because it is a single heterozygous variant in a condition caused by biallelic variants in DYSF, and we are not aware of any reports of dysferlinopathy associated with only a single pathogenic variant." (PMID 40175090, 2025). "Patients with DYSF mutations typically showed a later disease onset, the highest CK levels, and occasionally respiratory involvement, though none exhibited cardiac disease—again mirroring typical dysferlinopathy features." (PMID 40870035, 2025). "Deeper investigations on this, especially with a focus on the dysferlin’s partner proteins, with comprehensive functional analyses will likely identify modifiers of dysferlinopathies and their precise modifying role to explain the clinical heterogeneity of dysferlinopathies." (PMID 38540676, 2024). "Historically, although dysferlinopathies have been under study since their initial documentation in Japan in the 1970s, our understanding of the molecular intricacies of these conditions remains elusive, largely due to the incomplete understanding of dysferlin’s core functions." (PMID 38540676, 2024). "Notably, DYSF is a well‐established pathogenic gene associated with dysferlinopathy, and the reported gene mutation sites do not exhibit positional domain specificity." (PMID 39350328, 2024). "It is still unclear how dysferlin deficiency initially results in the severe pathology of only specific muscles; consequently, no effective treatments are currently available for dysferlinopathy patients." (PMID 39123261, 2024). "Complement C5b-9 has been reported to be deposited on the sarcolemma of non-necrotic and cytoplasm of necrotic fibers in dysferlin-deficient mice and in patients with dysferlinopathy, making it distinct from DMD where complement C5b-9 was exclusively identified in the cytoplasm of necrotic fibers." (PMID 35135626, 2022). "Despite the effects of dysferlin-deficiency on endothelial and vascular function, to date, atherosclerotic plaque development has not been explored in human patients or mouse models of dysferlinopathies." (PMID 34366880, 2021). "Recent research inferred that a drug inducing Dysferlin expression in myocytes could represent a targeted during clinical treatment for Dysferlinopathy patients, which also indicates that gene therapy could be an effective future clinical avenue for MMD patients." (PMID 34276779, 2021). "Since there are no other known models of dysferlinopathy in other species, locomotor proficiency and muscular anatomy through MRI (both lower leg and hip region) were evaluated in dysferlin‐deficient B6.A‐Dysfprmd/GeneJ (Bla/J) mice to define disease parameters for therapeutic assessment." (PMID 28320887, 2017). "Therefore, at least dysferlin exon 32 is thought to be a promising target of exon skipping therapy, although there are currently no ongoing or pending clinical trials involving AO-mediated therapy for dysferlinopathy." (PMID 25562650, 2013). "Our data suggest that the pathogenicity of dysferlin deficiency is not solely related to impairment in sarcolemmal repair and highlight the care needed in selecting assays to assess potential therapies for dysferlinopathies." (PMID 22666441, 2012).
dysferlinopathy (continued). "To assess whether elevated muscle PGC-1α ameliorates disease progression of dysferlin-deficient mice, analogous to previous findings in Duchenne muscular dystrophy and other muscle wasting models, we crossed skeletal muscle-specific PGC-1α transgenic mice with a model for dysferlinopathy." (PMID 40021220, 2025). "In muscle samples from dysferlinopathy patients, both AHNAK and dysferlin levels are reduced, with AHNAK showing a notable decrease in the sarcolemma but remaining stable in blood vessels, indicating a muscle-specific reduction." (PMID 38540676, 2024). "Dysferlinopathy includes a spectrum of muscle diseases characterized by three major phenotypes: MMD, LGMD2B, and DMAT." (PMID 38903757, 2024). "This can be challenging for dysferlinopathy due to the significant clinical overlap between the 30+ subtypes of limb–girdle muscular dystrophy (LGMD) and the large number of variants of unknown significance (VUSs) that are identified in the dysferlin gene, DYSF." (PMID 36983702, 2023). "Conversely, inhibition of proteasome activation results in a trend toward increased dysferlin and alleviates muscle inflammation, suggesting an important role of UPP in dysferlinopathy." (PMID 36203997, 2022). "Here, we show insufficient plasma membrane repair in fibroblasts from dysferlinopathy patients and SJL mice expressing truncated dysferlin." (PMID 26579332, 2015). "Immunohistochemistry demonstrated positive staining for C5b-9 and major histocompatibility complex class I on the myolemma, but negative staining for dysferlin, suggesting dysferlinopathy." (PMID 41517735, 2026). "Given the current lack of disease-modifying therapies for dysferlinopathies, ASO-mediated exon skipping has shown potential in bypassing disease-causing pathogenic variants to generate a truncated dysferlin protein with enhanced functionality." (PMID 39936969, 2025). "AAV-mediated gene therapy for dysferlinopathy involves introducing functional copies of the dysferlin gene into affected cells to compensate for the defective or absent dysferlin protein." (PMID 38891760, 2024). "Dysferlinopathy encompasses a category of neuromuscular diseases characterized by the absence of dysferlin in the skeletal muscle." (PMID 38903757, 2024). "We selected NM_003494.3: c.3477C > A (p.Y1159X) in exon 32 since it has been previously observed in three dysferlinopathy patients with a complete lack of dysferlin protein expression in muscle biopsies." (PMID 37239109, 2023). "The other nine cases have disease range/absent DYSF protein levels, which is highly correlated with a dysferlinopathy diagnosis." (PMID 36983702, 2023). "Phenotypic similarities between ANO5-myopathies and dysferlinopathies, lead to hypothesize that ANO5 may function in membrane repair comparable to DYSF." (PMID 34067866, 2021). "ANXA1 and ANXA2 interact with DYSF to mediate sarcolemma repair and both ANXA have been reported to be upregulated in Italian, American, or Australian patients suffering from dysferlinopathies." (PMID 34067866, 2021). "In conclusion, we did not observe a significant increase of dysferlin or myogenin in myotubes from a dysferlinopathy patient when treated with EB1089, oprozomib and ixazomib." (PMID 33246442, 2020). "Immunohistochemical analysis on muscle biopsy indicated an absence of dysferlin, conforming to dysferlinopathy." (PMID 33031319, 2020). "Presence of inflammation in muscle biopsy and absence of Dysferlin staining were the manifestations of dysferlinopathy at the histological level." (PMID 33250842, 2020). "Along the same lines, transgenic mice generated from the A/J mouse model of dysferlinopathy, expressing dysferlin under a skeletal muscle-specific promoter are indistinguishable from dysferlin-sufficient mice." (PMID 32106631, 2020). "Dysferlinopathies encompass a heterogeneous group of muscular disorders, which are characterized by the absence of dysferlin in skeletal muscles." (PMID 33031319, 2020).
dysferlinopathy (continued). "This led to further immunohistochemical testing on the previously obtained muscle biopsy specimen from our patient that demonstrated an absence of dysferlin staining, thus establishing the diagnosis of dysferlinopathy (LGMD2B)." (PMID 27195159, 2016). "In our present study, we showed that dysferlin is expressed in cultured skin fibroblasts from both humans and mice, however, there are no reports of skin abnormalities in dysferlinopathy patients or SJL mice." (PMID 26579332, 2015). "This minidysferlin was originally identified in a patient with a mild form of dysferlinopathy with little dystrophic features, in particular with a very low level of CNF and shown to restore the membrane repair capacity of dysferlin-null muscle, following laser wounding." (PMID 22666441, 2012). "No treatment is available for dysferlinopathies and gene therapy is complicated by the fact that the dysferlin cDNA is large." (PMID 22666441, 2012). "The analysis of dysferlin in PBM is very helpful to rule out a dysferlinopathy when no muscle sample is available." (PMID 22194990, 2011). "In these previous studies, dysferlinopathy cases were most commonly diagnosed based on a lack of dysferlin protein expression by immunostaining or Western blot analysis with only case reports or small series identifying cases by the presence of definitive pathogenic variants in DYSF." (PMID 35135626, 2022). "As there are no effective treatments for dysferlinopathies, we assessed whether inhibition of the ubiquitin proteasome system could prevent degradation of dysferlin in immortalized myoblasts from a patient carrying two missense mutations." (PMID 33246442, 2020). "Treatment with oprozomib, ixazomib and EB1089 in myotubes from a dysferlinopathy patient promoted a trend towards increased expression of dysferlin and myogenin, but this low increase did not translate into higher sarcolemmal repair neither higher fusion index than that in untreated myotubes." (PMID 33246442, 2020). "However, there is also evidence that inflammation in dysferlinopathies originates autonomously within the skeletal muscle and not due to dysferlin function in other cell types." (PMID 32106631, 2020). "In conclusion, fibroblasts from dysferlinopathy patients and SJL mice showed attenuated membrane repair, and could be a research tool to monitor the effects of drug candidate including proteasome inhibitors on mutant dysferlin." (PMID 26579332, 2015). "Her muscle biopsy confirmed rimmed vacuoles but immunocytochemistry for dysferlin was not available, resembling GNE-myopathy more than dysferlinopathy." (PMID 33250842, 2020). "The absence of labeling for dystrophins and dysferlin in FFPE sections was documented in all three DMD patients and the dysferlinopathy patient." (PMID 28219397, 2017). "We recommended that dysferlin levels in total PBMC may be useful in patients for whom muscle tissue is not available for study and to guide further testing in dysferlinopathies." (PMID 33613410, 2020). "The absence of labeling for dysferlin and the rod domain and C-terminus of dystrophin in FFPE sections was documented in all three DMD patients (patients 4, 6, and 8) and the dysferlinopathy patient (patient 3), allowing a diagnosis to be made using FFPE sections." (PMID 28219397, 2017).